EPB41L2 (erythrocyte membrane protein band 4.1 like 2)
Description:
Required for dynein-dynactin complex and NUMA1 recruitment at the mitotic cell cortex during anaphase.
Synonyms: 4.1G; 4.1-G
Tractability: Antibody: UniProt places it where antibodies can reach, with high confidence; its Gene Ontology location is reachable by antibodies, with high confidence; the Human Protein Atlas places it where antibodies can reach. PROTAC: UniProt records ubiquitination sites on it; ubiquitination databases record sites on it; its protein half-life has been measured.
Gene: Protein-coding gene on chromosome 6 (130,839,343 to 131,063,361, reverse strand). Ensembl gene ENSG00000079819.
Subcellular location: Cytoplasm, cytoskeleton; Cytoplasm, cell cortex; Cell membrane
Subcellular location (Human Protein Atlas): Plasma membrane; Cell Junctions; Nucleoplasm
Pathways (Reactome):
Neuronal System: Neurexins and neuroligins
Gene Ontology:
Molecular function: protein binding; actin binding; cytoskeletal protein binding; PH domain binding; spectrin binding; structural molecule activity
Biological process: positive regulation of protein localization to cell cortex; actomyosin structure organization; cortical actin cytoskeleton organization
Cellular component: cell cortex; cell junction; COP9 signalosome; extracellular exosome; focal adhesion; nucleoplasm; plasma membrane; cytoskeleton; cytosol; spectrin
Genetic constraint (gnomAD): Loss-of-function variants: 37 observed, 94.68 expected, observed/expected ratio (o/e) 0.39, 90% interval 0.3 to 0.51. The upper end of that interval is the gene's LOEUF score, 0.51, which puts it in group 2 of 6, group 1 being the genes least tolerant of losing a copy. Missense variants: 1,072 observed, 1,189.6 expected, observed/expected ratio (o/e) 0.9, 90% interval 0.86 to 0.95. Synonymous variants: 409 observed, 428.97 expected, observed/expected ratio (o/e) 0.95, 90% interval 0.88 to 1.03.
Homologues: Orthologues: chimpanzee EPB41L2 (99% identical), macaque EPB41L2 (98% identical), rabbit EPB41L2 (91% identical), pig EPB41L2 (89% identical), guinea pig EPB41L2 (84% identical), rat Epb41l2 (83% identical), mouse Epb41l2 (82% identical), dog EPB41L2 (82% identical), tropical clawed frog epb41l2 (58% identical), zebrafish EPB41L2 (50% identical), Drosophila melanogaster cora (31% identical), Caenorhabditis elegans frm-1 (31% identical), and 5 more. Paralogues in human: EPB41L3 (44% identical), EPB41 (44% identical), EPB41L1 (38% identical), EPB41L4B (21% identical), EPB41L5 (20% identical), FRMD5 (17% identical), FRMD3 (17% identical), EPB41L4A (17% identical), FRMD6 (14% identical), MYLIP (12% identical).
Diseases named in the same sentence as EPB41L2 in open-access papers:
EPB41L2 is named in the same sentence as 16 diseases in open-access papers, as found by Europe PMC text mining. Sharing a sentence is not in itself a finding about the gene and the disease. The quoted sentences say what the papers report.
ovarian carcinoma (3 papers, 2019 to 2025). A malignant neoplasm originating from the surface ovarian epithelium. "Overexpression of EPB41L2 in ovarian cancer has been reported to be associated with chemotherapy resistance." (PMID 34692669, 2021). "Thus, EPB41L2 may behave as an oncogene in ovarian cancer, although the association requires further investigations." (PMID 31195594, 2019). "This research underscores the potential of EPB41L2 as both a prognostic biomarker and a therapeutic target, paving the way for precision treatments aimed at overcoming chemoresistance in ovarian cancer." (PMID 40771481, 2025).
Alzheimer disease (1 paper, 2024). A progressive, neurodegenerative disease characterized by loss of function and death of nerve cells in several areas of the brain leading to loss of cognitive function such as memory and language. "In contrast, the gene EPB41L2 (1.079, 1.029 − 1.130, P = .001), MYO1F (1.083, 1.004 − 1.168, P = .039), and SSH2 (1.049, 1.015 − 1.083, P = .004) were associated with a higher risk of developing Alzheimer’s disease." (PMID 39560568, 2024).
bipolar disorder (1 paper, 2022). A disorder of the brain that causes unusual shifts in mood, energy, activity levels and the ability to carry out day-to-day tasks. "Other regulated genes by Sox13 might be associated to PD syndrome; for example, Nckap5 is considered the most promising candidate for bipolar disorder, and Epb41l2 gene is associated with cognitive impairment in the hippocampus induced by anesthesia." (PMID 36142685, 2022).
Cirrhosis (1 paper, 2022). A chronic disorder of the liver in which liver tissue becomes scarred and is partially replaced by regenerative nodules and fibrotic tissue resulting in loss of liver function. "Finally, up-regulation of alpha-actinin-1, Band 4.1-like protein 2 (EPB41L2), asparagine synthetase (ASNS), and down-regulation of heme oxygenase (HMOX1) are correlated with cirrhosis." (PMID 36016316, 2022).
glioma (1 paper, 2012). A benign or malignant brain and spinal cord tumor that arises from glial cells (astrocytes, oligodendrocytes, ependymal cells). "The exceptions are three genes (NTRK2, EPHB3, and EPB41L2), which are known to play a role in neural systems, and only appear in some of the core modules from the two cancer types of neural origin, gliomas and melanoma, and NSCLC that expresses prominent features of neuroendocrine cells." (PMID 22691569, 2012).
meningioma (1 paper, 2020). A generally slow growing tumor attached to the dura mater. "This study revealed the identification of phosphorylated sites of several proteins that were found to play a role in meningioma pathobiology by several studies including EPB41L2, NDRG2, SPTB, MAGED2, MXRA7, and nearly 51 Kinases which were also mapped further through Kinome Analysis." (PMID 32974197, 2020).
tumor (8 papers, 2019 to 2025). "Circ-EPB41L2 is downregulated in the exosomes of CRC patients, and exosome-mediated circ-EPB41L2 suppresses tumor progression by regulating the PTEN/AKT signaling pathway." (PMID 37525158, 2023). "Using qRT-PCR, we also verified that the gene AS events SORBS2 were downregulated in tumor tissue, and gene AS events EPB41L2, CELF2, TMEM130, and VCL were upregulated in tumor tissue." (PMID 34692669, 2021). "Interrogating published expression datasets against our SMG list found KIF24, KCNK5, EPB41L2, and ABI3BP downregulated in AK compared with those in the normal skin, suggesting tumor suppressor roles." (PMID 33482222, 2021). "We further examined the hub gene AS events and hub gene mRNA expression between five paired normal and tumor tissues by qRT-PCR, and found that the PSI of EPB41L2, TMEM130, and SORBS2 were different from tumor to normal." (PMID 34692669, 2021). "Four genes (EPB41L2, HLA-DQB1, LTF and SFRP1) were consistently overexpressed across multiple PFS cutoff times in initial tumor samples of patients with disease progression following topotecan treatment." (PMID 31195594, 2019). "Four genes (EPB41L2, HLA-DQB1, LTF and SFRP1) were consistently overexpressed in initial tumor samples of subsequent nonresponders across multiple PFS cutoff times." (PMID 31195594, 2019).
infection (1 paper, 2022). The state of being infected such as from the introduction of a foreign agent such as serum, vaccine, antigenic substance or organism. "EgPSC infection also caused the upregulation of Cgn, Epb41, Cldn8, Shroom3, Cask, Rab3b, Epb41l2, Csnk2b, Prkcb, and MyI12a." (PMID 36713407, 2022). "For example, several classic tight junction related genes (Ocln and Cldn4) were significantly downregulated post-infection, whereas other tight junctions-relative genes (Cldn8, Epb41L2, Prkcb, and Shroom3) were upregulated." (PMID 36713407, 2022).
EPB41L2 also shares sentences with these, for which no sentence is quoted: cancer (5 papers); Cognitive impairment (1); liver diseases (1); melanoma (1); neurological disorders (1); prostate adenocarcinoma (1); prostate carcinoma (1); steatosis (1).